ELF4 (E74 like ETS transcription factor 4)
Diseases named in the same sentence as ELF4 in open-access papers (continued):
Sharing a sentence is not in itself a finding about the gene and the disease.
cancer (continued). "In endometrial cancer, ELF4, acting as a transcriptional activator, is recruited to the promoter of catenin beta 1 (CTNNB1; encoding β-catenin) by tribbles pseudokinase 3 (TRIB3), thereby enhancing oncogenesis and self-renewal of cancer stem cells." (PMID 40083328, 2025). "ELF4 is involved in the proliferation regulation in multiple cancers." (PMID 40083328, 2025). "Dysregulation of ELF4 contributes to the occurrence of diseases including cancer." (PMID 40083328, 2025). "A pan-cancer bioinformatic analysis demonstrated overexpressed ELF4 could result in an aggressive cancer phenotype and sensitivity to anti-cancer drugs, such as Dasatinib, WH-4-023, and Ponatinib5." (PMID 39132148, 2024). "Recent research reveals the potential of ELF4 as a promising biomarker for cancers." (PMID 39132148, 2024). "Meanwhile, ELF4 is verified to affect ESCC cancer stemness by regulating FUT9 expression." (PMID 37674363, 2023). "Interestingly, several studies demonstrated that the deregulation of ELF4 contributes to the initiation and progression of human cancers." (PMID 36923538, 2023). "However, we know far less about how the expression of ELF4 affects the aggressiveness of disease across many human cancer types and their response to drug perturbations." (PMID 33836003, 2021). "Also, mutations in the coding sequence and mRNA expression variations of ELF4 have been reported in various human cancers." (PMID 33836003, 2021). "Comparison of other ELF family members showed ELF1 and ELF4 were also more highly expressed in AML than all other cancers, suggesting that they may play a role in AML." (PMID 28351373, 2017). "Furthermore, ELF4 exhibits pro-proliferative effects in cancer." (PMID 40083328, 2025). "Thus, it is crucial to illustrate the context-dependent roles of ELF4 in cancer." (PMID 40083328, 2025). "Furthermore, we demonstrate that ELF4 could promote cancer cell proliferation, migration, invasion, and stemness byin vivo assays." (PMID 37674363, 2023). "Thus, in this study, we found that ELF4 might promote the progression of ESCC by increasing ESCC cancer stem-like properties." (PMID 37674363, 2023). "Knockdown of ELF4 in EC cell lines (AN3CA, HEC‐1A) and patient‐derived EC cells suppressed proliferation, cell cycle progression, and cancer stem cell (CSC) activity." (PMID 41287970, 2025). "ELF4 can complex with TRIB3 to promote CDK6 expression, which is involved in EC cell proliferation and cancer stemness activities." (PMID 41287970, 2025). "From the results of these assays, ELF4 was validated to augment ESCC proliferation, migration, invasion, and cancer stem-like properties." (PMID 37674363, 2023). "The results of the immunohistochemistry show that ELF4 is overexpressed in ESCC tissues and is significantly correlated with cancer staging and prognosis." (PMID 37674363, 2023). "The frequency of somatic mutations increases with age in both non-cancerous and cancer tissue; therefore we suggest that the link between the expression of ELF4 and the mutation burden could be exploited to establish therapeutics that are more effective in treating specific cancers." (PMID 33836003, 2021). "ELF4 overexpression in these cancer cell lines inhibits the proliferation of cancer cells, while the overexpression of the ELF4 mutant (E211M) does not have this effect because E211M loses its DNA-binding ability." (PMID 41300273, 2025). "Furthermore, the results of the western blot analysis in these tumors validated that the expression levels of the cancer stemness markers CD44 and CD133 were decreased in the sh-ELF4 group." (PMID 37674363, 2023). "Additionally, the expression levels of both ELF4 and FUT9 were significantly positively correlated with the expressions of the cancer stemness markers CD44 and CD133." (PMID 37674363, 2023).
cancer (continued). "In addition to the observed positive correlation between ELF4 or FUT9 and the cancer stemness-related markers CD44 and CD133, our immunohistochemistry results revealed a significant positive correlation between the expressions of ELF4 and FUT9." (PMID 37674363, 2023). "However, most of the molecular mechanisms of ELF4 in cancer are not yet clarified." (PMID 40083328, 2025).
infection (5 papers, 2017 to 2025). The state of being infected such as from the introduction of a foreign agent such as serum, vaccine, antigenic substance or organism. "During pathogen invasion, ELF4 expression levels are rapidly upregulated to increase type I IFN expression levels to protect against pathogenic infection." (PMID 41300273, 2025). "The STING/IRFs/ELF4 axis is therefore important for Dpo induced ISGs expression, and can be used by host to counteract infection." (PMID 29124042, 2017). "Research has demonstrated ELF4’s significant roles in maintaining intestinal barrier integrity, promoting microbial balance, modulating inflammatory responses in the gut, and enhancing anti-infection defenses." (PMID 41300273, 2025).
hematological malignancies (1 paper, 2020). "This includes ELF4 which is known for its role in immune response and hematological malignancies but may also regulate functions required for both lung and brain metastasis." (PMID 32143622, 2020).
intestinal diseases (1 paper, 2025). "Future research into ELF4 and its downstream pathways will further elucidate the molecular basis of intestinal diseases, paving the way for more effective therapies and offering new hope for patients suffering from these prevalent disorders." (PMID 41300273, 2025). "Mechanistic studies could help identify diets or antimicrobials that activate intestinal ELF4 to combat pathogen/virus-induced intestinal diseases." (PMID 41300273, 2025). "Therefore, we can develop diets and drugs that activate intestinal ELF4 to prevent/treat intestinal diseases." (PMID 41300273, 2025).
kidney (1 paper, 2023). "In I/R induced kidney injury, to understand the involvement of ELF4 and whether this influences were related to OS and ERS, we assessed the change of OS index (SOD, CAT, and GSH-PX), OS related proteins (Nrf2, HO-1, and NQO-1), and ERS related proteins (GRP78, CHOP, and caspase-12)." (PMID 37474923, 2023).
ELF4 also shares sentences with these, for which no sentence is quoted: prostate carcinoma (3 papers); alcoholic liver diseases (2); Behçet’s disease (2); breast carcinoma (2); Hepatic fibrosis (2); prostate tumor (2); acute monocytic leukemia (1); Alcohol (1); Arthritis (1); atherosclerosis (1); breast invasive carcinoma (1); chronic granulomatous disease (1); Chronic Myeloid Leukemia (1); dermatitis (1); diffuse large B-cell lymphoma (1); Fever (1); fragile X syndrome (1); hepatocellular carcinoma (1); immune thrombocytopenia (1); kidney chromophobe (1); leukemia (1); liver cirrhosis (1); megakaryoblastic leukemia (1); metastatic tumours (1); oesophageal adenocarcinomas (1); oral carcinoma (1); pancreatic adenocarcinoma (1); Premature Ovarian Failure (1); prostate adenocarcinoma (1); systemic lupus erythematosus (1).
A further 2 diseases each share a sentence with ELF4 in 1 paper.